ST13 (ST13 Hsp70 interacting protein)
Description:
One HIP oligomer binds the ATPase domains of at least two HSC70 molecules dependent on activation of the HSC70 ATPase by HSP40. Stabilizes the ADP state of HSC70 that has a high affinity for substrate protein. Through its own chaperone activity, it may contribute to the interaction of HSC70 with various target proteins (By similarity).
Synonyms: Hip; AAG2; FAM10A1; SNC6; HSPABP1; P48; FAM10A4; HOP; HSPABP; PRO0786
Tractability: PROTAC: ubiquitination databases record sites on it; its protein half-life has been measured.
Gene: Protein-coding gene on chromosome 22 (40,824,535 to 40,856,690, reverse strand). Ensembl gene ENSG00000100380.
Subcellular location: Cytoplasm
Subcellular location (Human Protein Atlas): Cytosol; Basal body; Primary cilium; Primary cilium tip
Pathways (Reactome):
Cellular responses to stimuli: Regulation of HSF1-mediated heat shock response
Gene Ontology:
Molecular function: protein binding; Hsp70 protein binding; protein-macromolecule adaptor activity; protein dimerization activity
Biological process: protein folding
Cellular component: extracellular exosome; cytoplasm
Genetic constraint (gnomAD): Loss-of-function variants: 11 observed, 30.17 expected, observed/expected ratio (o/e) 0.36, 90% interval 0.23 to 0.6. The upper end of that interval is the gene's LOEUF score, 0.6, which puts it in group 2 of 6, group 1 being the genes least tolerant of losing a copy. Missense variants: 284 observed, 347.97 expected, observed/expected ratio (o/e) 0.82, 90% interval 0.74 to 0.9. Synonymous variants: 99 observed, 109.54 expected, observed/expected ratio (o/e) 0.9, 90% interval 0.77 to 1.07.
Homologues: Orthologues: chimpanzee ST13 (100% identical), macaque ST13 (99% identical), guinea pig St13 (94% identical), mouse St13 (94% identical), pig ST13 (93% identical), rat Slc25a17 (88% identical), rat St13-ps2 (82% identical), tropical clawed frog st13 (75% identical), zebrafish st13 (69% identical), Drosophila melanogaster HIP (42% identical), Drosophila melanogaster HIP-R (42% identical), Drosophila melanogaster Spag1 (24% identical). Paralogues in human: SPAG1 (21% identical), RPAP3 (20% identical), UNC45B (18% identical), UNC45A (18% identical), STIP1 (17% identical), TTC4 (17% identical), SPATA16 (15% identical), TTC31 (15% identical), SGTA (14% identical), TTC1 (14% identical), SGTB (14% identical), STUB1 (14% identical), and 6 more.
Diseases named in the same sentence as ST13 in open-access papers:
ST13 is named in the same sentence as 32 diseases in open-access papers, as found by Europe PMC text mining. Sharing a sentence is not in itself a finding about the gene and the disease. The quoted sentences say what the papers report.
colorectal cancer (4 papers, 2012 to 2020). A primary or metastatic malignant neoplasm that affects the colon or rectum. "Our recent findings suggest that overexpression of ST13 gene can inhibit the growth of colorectal cancer cells." (PMID 23077639, 2012). "The expression level of this protein is significantly downregulated in colorectal cancer, and increased of ST13 protein expression can suppress the proliferation of colorectal cancer cells." (PMID 23077639, 2012). "ST13 is an inhibitor of cell proliferation, colony formation, and cell migration and could induce apoptosis in colorectal cancer." (PMID 32432045, 2020). "Furthermore, ST13, a colorectal cancer-specific tumor suppressor gene, was inserted into a CRAds under the control of CEA promoter resulting in significant levels of apoptosis in colon cancer cells." (PMID 29534501, 2018). "Thus, ST13 was a candidate tumor-suppressor gene involved in colorectal carcinoma." (PMID 23077639, 2012). "Thus, several recombinant oncolytic adenoviruses regulated by the CEA promoter and delivering tumor suppressor genes, such as ST13, TRAIL, and Mn-SOD, were constructed in our laboratory and exhibit potent activity against colorectal cancer, pancreatic ductal adenocarcinoma, and lung cancer." (PMID 33322272, 2020).
lung carcinoma (4 papers, 2017 to 2021). "Furthermore, the level of HSP70 to its cochaperone DNAJ/HSP40 does not seem to change between benign lung disease and cancer in contrast with a higher level of ST13 to DNAJ associated with lung cancer." (PMID 34692733, 2021).
diabetics (1 paper, 2023). "In particular, beta cells of diabetics exhibited decreased expression of genes encoding molecular chaperones belonging to the heat shock families Hsp70 (HSPA1B, HSPA7, and HSPA8) and Hsp90 (HSP90AA1 and HSP90AB1) as well as co-chaperones (BAG3 and ST13) and nucleoporins (NDC1, NUP160, and POM121C)." (PMID 37569434, 2023).
Huntington disease (1 paper, 2022). Huntington disease (HD) is a rare neurodegenerative disorder of the central nervous system characterized by unwanted choreatic movements, behavioral and psychiatric disturbances and dementia. "In the “SP70 and HSP40-dependent folding in Huntington’s disease” pathway, ST13 is related to the folding process of mutant Huntington via stimulation of HSP70." (PMID 35804531, 2022).
laryngeal carcinoma (1 paper, 2021). Carcinoma that arises from the laryngeal epithelium. "This suggests that EGFR and INHBA can serve as prognostic hub genes for laryngeal cancer collectively with pRS genes (CFLAR, DAPK2, TSC2, CAPN10, MBTPS2, PEX14, FADD and ST13)." (PMID 34093817, 2021).
lipid metabolic disorder (1 paper, 2022). "Our data identified St13 as a critical protein in acinar lipid metabolic disorder in CP." (PMID 35562743, 2022).
muscular atrophy (1 paper, 2025). The loss of muscle tissue due to inactivity or disease. "Other relevant genes, such as TLL2, CH25H, and ST13, affect muscular atrophy and adipocyte differentiation." (PMID 41373569, 2025).
steatosis (1 paper, 2022). Increased lipid within the cytoplasm of cells. "Our data revealed that Sdf2l1 within the St13-Sdf2l1 complex plays a protective role in acinar injury and steatosis through regulation of the AA pathway." (PMID 35562743, 2022). "The molecular co-chaperone St13 was overexpressed in the pancreatic tissues of CP model mice and patients and found to protect against acinar steatosis and injury." (PMID 35562743, 2022). "In CP, St13 plays a protective role in acinar steatosis by binding Sdf2l1." (PMID 35562743, 2022).
tumor (9 papers, 2013 to 2024). "Notably, 8 autophagy-related genes (CAPN10, DAPK2, MBTPS2, ST13, CFLAR, FADD, PEX14 and TSC2) and 2 immune cells (Mast cells and Eosinophils) were revealed to be highly associated with tumor prognosis." (PMID 34093817, 2021). "ST13 was commonly downregulated in all tumor types compared to normal tissue." (PMID 31159852, 2019). "In particular CASP2, JNK2, PDCD10, and ST13 have been associated with mitochondrial permeabilization and with the induction of the apoptotic process, while SPARC overexpression seems to play a tumor suppressor function in some low expressing SPARC AMLs." (PMID 24148231, 2013). "Interestingly, most CIDGS-related genes, such as XRCC6, ST13, PES1, EFHD2, APOL2, ACTR2, and CDCP1, were markedly upregulated in HNSCC tumor samples, whereas several other genes, such as MARCO, MRC1, and CD83, were upregulated in healthy samples." (PMID 38666027, 2024). "Heat shock-activated HSF1 is mainly responsive to the expression of heat shock proteins, while activation of HSF1 in tumor tissues is predominantly responsible for controlling the expression of non-heat shock proteins, e.g. CKS2, LY6K, RBM23, CCT6A, CKS1B, ST13 and EIF4A2." (PMID 25199534, 2014).
cancer (8 papers, 2012 to 2023). A tumor composed of atypical neoplastic, often pleomorphic cells that invade other tissues. "The ST13 may be involved in various types of cancers by regulating the functions of different target proteins through cellular chaperone/co-chaperone pathways." (PMID 23077639, 2012). "No report was found on the role of ST13 in the kidney disease, whereas most of studies about ST13 are about the cancer biology." (PMID 35351150, 2022).
ST13 also shares sentences with these, for which no sentence is quoted: breast carcinoma (4 papers); osteosarcoma (3); infection (2); Spinocerebellar ataxia autosomal recessive 16 (2); Alzheimer disease (1); autosomal recessive cerebellar ataxia (1); bunyavirus infection (1); Cerebral ischemia (1); chronic pancreatitis (1); colon carcinoma (1); endometriosis (1); frontotemporal dementia (1); kidney disease (1); neurodevelopmental disorder (1); neurologic disorders (1); osteoporosis (1); ovarian carcinoma (1); pancreatic ductal adenocarcinoma (1); Pick disease (1); progressive supranuclear palsy (1); Sepsis (1); ZIKV infection (1).